KLHL6 (kelch like family member 6)
Description:
Substrate-specific adapter of a BCR (BTB-CUL3-RBX1) E3 ubiquitin ligase complex that acts as a multifunctional regulator of B-cell receptor (BCR) signaling, germinal center formation, and T-cell function. Functions by mediating polyubiquitination of target proteins, leading to their proteasomal degradation. In B-cells, plays an essential role in BCR signaling and germinal center B-cell maturation. Targets the BCR signaling subunits CD79A and CD79B for ubiquitin-mediated degradation, thereby controlling surface BCR homeostasis. Mediates polyubiquitination and degradation of the mRNA decay factor roquin-2/RC3H2, which in turn allows accumulation of TNFAIP3, a negative regulator of NF-kappa-B signaling, thereby providing feedback inhibition of BCR-induced NF-kappa-B activation. In T-cells, acts as a dual negative regulator of T-cell exhaustion and mitochondrial dysfunction. Promotes 'Lys-48'-linked polyubiquitination and proteasomal degradation of the transcription factor TOX, thereby attenuating the transition of progenitor exhausted T-cells towards terminal exhaustion. Also targets the mitochondrial phosphatase PGAM5 for degradation, thereby preventing excessive PGAM5-mediated dephosphorylation and activation of DRP1, which would otherwise drive pathological mitochondrial fission. Through these mechanisms, maintains mitochondrial fitness in T-cells during chronic antigen stimulation.
Synonyms: FLJ00029
Tractability: Small molecule: it belongs to a druggable protein family. Antibody: the Human Protein Atlas places it where antibodies can reach. PROTAC: ubiquitination databases record sites on it.
Gene: Protein-coding gene on chromosome 3 (183,487,551 to 183,555,706, reverse strand). Ensembl gene ENSG00000172578.
Subcellular location: Cytoplasm
Subcellular location (Human Protein Atlas): Centriolar satellite; Plasma membrane; Cytosol; Microtubules; Mitotic spindle
Gene Ontology:
Molecular function: protein binding; ubiquitin-like ligase-substrate adaptor activity
Biological process: proteasome-mediated ubiquitin-dependent protein catabolic process; B cell receptor signaling pathway; germinal center formation
Cellular component: cytoplasm; Cul3-RING ubiquitin ligase complex
Genetic constraint (gnomAD): Loss-of-function variants: 39 observed, 54.82 expected, observed/expected ratio (o/e) 0.71, 90% interval 0.55 to 0.93. The upper end of that interval is the gene's LOEUF score, 0.93, which puts it in group 3 of 6, group 1 being the genes least tolerant of losing a copy. Missense variants: 707 observed, 824.09 expected, observed/expected ratio (o/e) 0.86, 90% interval 0.81 to 0.91. Synonymous variants: 335 observed, 336.05 expected, observed/expected ratio (o/e) 1, 90% interval 0.91 to 1.09.
Homologues: Orthologues: chimpanzee KLHL6 (99% identical), macaque KLHL6 (99% identical), rabbit KLHL6 (96% identical), mouse Klhl6 (94% identical), rat Klhl6 (91% identical), dog KLHL6 (89% identical), guinea pig KLHL6 (86% identical). Paralogues in human: KLHL24 (43% identical), KLHL35 (34% identical), KLHL20 (29% identical), KLHL3 (28% identical), KLHL2 (28% identical), KLHL12 (28% identical), KLHL21 (27% identical), KLHL28 (27% identical), KLHL5 (27% identical), KLHL1 (27% identical), KLHL38 (27% identical), KLHL4 (27% identical), and 42 more.
Diseases named in the same sentence as KLHL6 in open-access papers:
KLHL6 is named in the same sentence as 19 diseases in open-access papers, as found by Europe PMC text mining. Sharing a sentence is not in itself a finding about the gene and the disease. The quoted sentences say what the papers report.
chronic lymphocytic leukemia (5 papers, 2013 to 2025). "KLHL6 is involved in B-lymphocyte antigen receptor signaling and its variants have been associated with B-cell lymphomas and chronic lymphocytic leukemias." (PMID 32150563, 2020). "An example is the transcription factor KLHL6, which has previously been implicated in B cell receptor signaling and is recurrently mutated in chronic lymphocytic leukemia." (PMID 27357150, 2016). "Mutations in KLHL6 are recurrent in cases of chronic lymphocytic leukemia (CLL), a type of leukemia that is predominant in adults." (PMID 23676014, 2013). "Among the genes belonging to this family, KLHL25, KLHL3, and KLHL6 were found to be up-regulated by the fluorinated chalcone; curiously, these genes have been described to inhibit cell migration and invasiveness in lung carcinoma, diffuse large B-cell lymphoma, and chronic lymphocytic leukemia." (PMID 40332279, 2025).
diffuse large B-cell lymphoma (5 papers, 2021 to 2025). "As the tumor suppressor gene, the deficiency of KLHL6 will promote NF-κB activation to drive diffuse large B-cell lymphoma proliferation and promote inflammation." (PMID 39065139, 2024). "KLHL6 mutations have been described to disrupt this ligase function and to contribute to the growth of diffuse large B-cell lymphoma (DLBCL) cells in vitro and in vivo." (PMID 34465776, 2021). "CRL3 adaptors have critical roles in cancer pathogenesis and hotspot inactivating mutations have been identified in the substrate recruitment domain of Kelch-like protein 6 (KLHL6), favouring the growth of diffuse large B-cell lymphoma." (PMID 35379950, 2022). "For example, KLHL6 that involved in B‐lymphocyte antigen receptor signaling and germinal‐center B‐cell maturation shows connection with all the three lncRNA and many predicted miRNAs in both the ceRNA networks and is reported to be a tumor suppressor in diffuse large B‐cell lymphoma." (PMID 38506253, 2024).
lymphoma (4 papers, 2020 to 2024). A malignant (clonal) proliferation of B- lymphocytes or T- lymphocytes which involves the lymph nodes, bone marrow and/or extranodal sites. "Together, our findings reshape the pathogenic role of KLHL6 mutations in lymphoma, which have previously been postulated as passenger mutations arising from aberrant somatic hypermutation or resulting in complete loss of function." (PMID 38630892, 2024). "In this regard, it is of interest that also in this disorder the clonally expanded rogue B-cells harbor mutations of lymphoma-related genes (CARD11, TNFAIP3, CCND3, ID3, BTG2, KLHL6)." (PMID 39055707, 2024). "When unchallenged, U2932 and SuDHL5 cells with various KLHL6 manipulations grew at a similar rate, however, silencing of KLHL6-sensitized and WT overexpression desensitized lymphoma cells for activation-induced cell death (AICD)." (PMID 38630892, 2024). "Finally, to address these strikingly different phenotypes that the different KLHL6 mutants induced to lymphoma cells, we sought to investigate their molecular characteristics beyond the BCR components." (PMID 38630892, 2024).
B-cell lymphomas (3 papers, 2020 to 2024). "Loss of KLHL6 expression and mutant-induced phenotypes associate with targetable disease characteristics in B-cell lymphoma." (PMID 38630892, 2024). "Proteomic screening and functional investigation of E3 ubiquitin ligase substrate-adapter KLHL6 reveal a new role targeting B-cell receptor, which is disrupted in a subset of B-cell lymphomas with targetable phenotypic characteristics." (PMID 38630892, 2024). "KLHL6 was first cloned from ovine Peyer’s patch tissues, and its expression is restricted to human GC B cells and most GC-originating B-cell lymphomas." (PMID 38630892, 2024).
breast carcinoma (2 papers, 2022 to 2024). "FGFR1 and KLHL6 mutations are protective factors for radiation-induced skin toxicity in breast cancer patients." (PMID 38380359, 2024). "Subsequently, we will attempt to conduct further studies using a larger cohort of patients with breast cancer to elucidate the association of FGFR1 and KLHL6 or other novel gene mutations with acute radiation skin reactions and consider the potential confounding effects of clinical factors." (PMID 38380359, 2024).
acute myeloid leukemia (1 paper, 2021). Acute myeloid leukemia (AML) is a group of neoplasms arising from precursor cells committed to the myeloid cell-line differentiation. "In a later study, it was verified that Kelch-like protein 6 (KLHL6), as an E3 ubiquitin ligase, plays an important role in acute myeloid leukemia (AML) by regulating the expression of CDK2." (PMID 34072267, 2021).
adenoid cystic carcinoma (1 paper, 2015). A malignant tumor arising from the epithelial cells. "Among other salivary gland neoplasms, genomic alterations in FBXW7, KLHL6, and LRP1B have been identified in adenoid cystic carcinoma." (PMID 26634163, 2015).
atrophic gastritis (1 paper, 2023). "KLHL6 protein was much higher than that in atrophic gastritis, intestinal metaplasia and dysplasia in benign gastric disease specimens in GC tissues, and KLHL6 significantly enhanced the expression of proliferation-related genes HGF, MMP-2 and VEGF-C in GC cells." (PMID 37803421, 2023).
Autoimmunity (1 paper, 2024). The occurrence of an immune reaction against the organism's own cells or tissues. "We expect our findings will unlock the exploration of therapeutic BCR targeting following KLHL6 dysregulation in B-cell neoplasia and autoimmunity." (PMID 38630892, 2024).
gastric cancer (1 paper, 2022). A primary or metastatic malignant neoplasm involving the stomach. "The findings suggested that, in gastric cancer, KLHL6 expression is lower in tumor tissues, and mice experiments revealed that the downregulation of KLHL6 expression also suppresses tumor growth." (PMID 36185403, 2022). "KLHL6 expression levels in tumor tissue have prognostic value in gastric cancer." (PMID 36185403, 2022).
tumor (8 papers, 2013 to 2025). "We also identified mutations in the tumor suppressor KLHL6 in 8%." (PMID 34465776, 2021). "Examining KLHL6 in the tumor tissues of patients treated with these regimens could reveal a biomarker role for KLHL6 mutations and KLHL6GC+ phenotype to predict responses besides being a prognostic marker in the ABC DLBCL." (PMID 38630892, 2024). "In addition to recapitulating known alterations, MutComFocal identifies ARID1B, ROBO2 and MRS1 as candidate tumor suppressors and KLHL6, IL31 and LRP1 as putative oncogenes in DLBCL." (PMID 23531283, 2013).
cancer (4 papers, 2013 to 2022). A tumor composed of atypical neoplastic, often pleomorphic cells that invade other tissues. "KLHL6, HAO2, and OSR2 have been shown to be involved in the prognosis of other cancers." (PMID 36185403, 2022).
KLHL6 also shares sentences with these, for which no sentence is quoted: diabetes (1 paper); dysplasia (1); infection (1); leukemia (1); lung carcinoma (1); lung disease (1); salivary gland neoplasm (1).